LEP (leptin)
Diseases named in the same sentence as LEP in open-access papers (continued):
Sharing a sentence is not in itself a finding about the gene and the disease.
Obesity (continued). "Some nucleotide variations (SNVs) in obesity-related genes, such as LEP 2548G/A and 668A/G in the LPR and LPL, have been associated with preeclampsia." (PMID 35252239, 2022). "Positive association was observed for leptin, CRP, fasting insulin, and estradiol, when comparing women with obesity or overweight versus normal weight." (PMID 35048536, 2022). "Obesity leads to an increase in the level of leptin and resistin and a decrease in the level of adiponectin in the serum." (PMID 36295052, 2022). "This hypothalamic inflammation is involved in the process of leptin and insulin resistance, leading to obesity and, quite possibly, diabetes." (PMID 36290695, 2022). "Obesity results in significant changes in the adipokine profile, creating a shift towards elevated pro-inflammatory adipokines such as leptin and resistin and reduced levels of anti-inflammatory adipokines such as adiponectin and ZAG." (PMID 35909571, 2022). "Further study is needed to define the importance of leptin production in this genetic-induced obesity model." (PMID 36865784, 2022). "Due to the antagonistic role of adiponectin and leptin in the obesity context, we decided to analyze the ratio of adiponectin/leptin at 6 and 12 months of age in all tested groups." (PMID 35379852, 2022). "Molecular mechanisms are activated by leptin, as adipokine with a central role in the connection between breast neoplasm and obesity has been discovered." (PMID 35989732, 2022). "In obesity, the accumulation of visceral fat affects adipokines in adipose tissue including leptin and adiponectin." (PMID 35164174, 2022). "This suggests that KSR2 exerts opposite effects on leptin and complement factor D/adipsin expression in fat tissues, which is consistent with changes observed in other models of obesity in mice." (PMID 36342465, 2022). "Leptin is overexpressed in adipose tissue in cases of obesity, as well as due to resistance mechanisms leading to leptin’s inability to reach targeted cells, decreased leptin receptor (LEPR) expression, or altered signaling." (PMID 35563103, 2022). "In the obesity-associated TIME, elevated fatty acid levels inhibit glycolysis in effector CD8+ T cells through the leptin/PD-1-STAT3 pathway and reduce anti-tumor activity." (PMID 36611881, 2022). "Silencing of leptin in adipose-derived stromal cells from patients with obesity led to reduced MCF-7 tumor cell expression of markers associated with EMT and reduced metastasis." (PMID 35435599, 2022). "In contrast, drugs aiming to increase the sensitivity to leptin are among the most promising pharmacological alternatives to treat obesity." (PMID 35742928, 2022). "Serum samples measured with the obesity plate also revealed reductions in both leptin and glucagon across the study period." (PMID 35574470, 2022). "The bioinformatic methods are used to find therapeutic targets of melatonin in the treatment of leptin resistance-induced obesity." (PMID 35937803, 2022). "In the women, the plasma leptin concentrations were significantly increased in the group D patients with severe obesity compared to the controls." (PMID 35629157, 2022). "Adiponectin to leptin ratio (LAR) has been mainly studied in the context of obesity-related disorders such as cardiometabolic diseases, diabetes and metabolic syndrome." (PMID 34977280, 2022). "Corroborating our results, previous studies also showed an increase in serum leptin levels in experimental models of obesity induced by high-fat diets." (PMID 36466412, 2022). "DIO mice had serum leptin levels 40-times higher than ob/ob animals, more closely reflecting obesity in humans." (PMID 35860241, 2022). "In obesity, the insulin and leptin resistance occurring in immune cells can be traced to an increased SOCS1/3." (PMID 35406000, 2022).
Obesity (continued). "This rodent model, in a C57BL/6J background, is unable to produce leptin—a hormone responsible for inhibiting hunger—via altering the leptin gene (i.e., ob or Lep), leading to increased appetite and obesity." (PMID 35128745, 2022). "In mice, LEPROT knockdown showed high leptin sensitivity and was resistant to diet-induced obesity, and it was thought to be a candidate for regulating leptin sensitivity." (PMID 36011333, 2022). "Taken together, these studies suggest a positive association between circulating leptin levels and NAFLD and also with degree of NAFLD in children and adolescents with obesity." (PMID 35677722, 2022). "Independently of obesity, IH can itself induce leptin secretion via activating the sympathetic nervous system, renin–angiotensin system and hypothalamic–pituitary–adrenal axis." (PMID 36359273, 2022). "Leptin, a key player in growth stimulation in obesity, inhibits apoptosis, largely by increasing the expression of the anti-apoptotic proteins B-cell lymphoma 2 (Bcl-2) and survivin." (PMID 36038791, 2022). "The results showed higher plasma leptin levels in newborn male mice from the maternal obesity group than in the control group (p < 0.01)." (PMID 35327669, 2022). "The effects of chronic exercise on leptin and adiponectin levels in children and adolescents with obesity are uncertain." (PMID 36554976, 2022). "Contrary to leptin, adiponectin levels appear to be decreased in subjects with impaired lung function and obesity." (PMID 35806353, 2022). "Low serum leptin level was observed in one obesity subject (P291) (BMI 26.3 kg/m2 with serum leptin 7.41 ng/ml) and one overweight subject (C155) (BMI 23.4 kg/m2 with serum leptin 4.36 ng/ml)." (PMID 36619235, 2022). "Leptin and adiponectin are the markers most frequently used to assess the relationship between the inflammation of obesity and that of asthma." (PMID 35807067, 2022). "The connection between obesity and the pathophysiological mechanisms governing autoimmune disease development has been most thoroughly documented for the adipokine leptin." (PMID 36479348, 2022). "In vitro studies indicate for example a decrease of leptin by virgin olive oil components making it a potentially promising therapeutic agent for the treatment and prevention of obesity." (PMID 36141644, 2022). "In obese mice and humans with disrupted leptin signaling, blood pressure is low compared to diet-induced obesity in rodents and obesity in humans, and leptin appears to play a major role in the increase in blood pressure that occurs with weight gain." (PMID 36499740, 2022). "The discrepancies of leptin changes associated with short sleep time could be in part due to different characteristics of patient populations (e.g., age, BMI, and prevalence of diabetes and obesity) and different methods of sleep measurement (e.g., polysomnography vs. self-report sleep time)." (PMID 35163627, 2022). "Overall, in this section we have seen that obesity leads to a state of systemic and local metabolic dysregulation, which is likely to be affected by altered levels of circulating leptin." (PMID 36855701, 2022). "This has implications for increasing the inflammatory response and leukocyte infiltration into the lung in individuals with increased leptin levels, such as during obesity." (PMID 35273609, 2022). "All the indexes examined including the circulating leptin, triglyceride, and total cholesterol, as well as food intake and weight gain, demonstrated a positive effect of the iPRTi strategy on obesity control." (PMID 35774455, 2022). "Below we discuss the most studied adipokines, leptin and adiponectin, and how alterations in these adipokines contribute to obesity-related CKD." (PMID 36726470, 2022). "ROS play a direct role in adipogenesis, and oxidative stress modulates several factors involved in obesity, including genetic factors, gut microbiota, insulin action, ghrelin, inflammation, adipokines, leptin, and the hypothalamic axis." (PMID 36290635, 2022).
Obesity (continued). "The people with obesity having AA genotype showed an increase in the mean serum leptin level in comparison with AG and GG genotypes." (PMID 36619235, 2022). "We assume that these pre-pubertal children with obesity have too low circulating leptin levels related to their BMI." (PMID 35677722, 2022). "Adiponectin mediates anti-atherosclerotic, anti-inflammatory, and anti-hyperglycemic actions, and in contrast to leptin, its level decreases in cases of IR and obesity." (PMID 35501770, 2022). "Among adipokines, the most important member is leptin, whose circulating levels directly correlate with BMI and obesity." (PMID 35053431, 2022). "Heterozygous BDNF knockout mice had reduced BDNF expression which led to age-dependent obesity and an insulin-resistant phenotype, and were characterised by elevated circulating levels of insulin, leptin and glucose." (PMID 36008755, 2022). "Leptin and ghrelin hormones are directly related to suppressing and increasing the desire for food intake, and obesity is also known to be related to leptin resistance." (PMID 35204193, 2022). "In obesity, the endocrine function of adipocytes is changed, with decreased adiponectin and increased levels of leptin, resistin, IL-6, and tumor necrosis factor (TNF)." (PMID 36299943, 2022). "Injury of hypothalamus, enhanced by obesity, disrupts the effects of several metabolic hormones (ghrelin, insulin, leptin, glucagon-like peptide 1 (GLP-1)), which are key regulators of appetite." (PMID 35887234, 2022). "Blood adiponectin and leptin are adipokines that emerged as potential biomarkers for predicting Alzheimer’s disease (AD) owing to their strong connection with obesity." (PMID 36329496, 2022). "What’s more, pharmacological leptin therapy for the treatment of diet-induced obesity has been reported to be ineffective, which is the famed “leptin resistance” phenomenon." (PMID 35774455, 2022). "High-fat diet (HFD) consumption is known to trigger an inflammatory response in the brain that prompts the dysregulation of energy balance, leads to insulin and leptin resistance, and ultimately obesity." (PMID 36507349, 2022). "Addressing brain-related mechanisms, we have repeatedly shown that obesity-induced leptin resistance is normalized by TEL, as leptin can once again cross the blood‒brain barrier." (PMID 35431918, 2022). "Reportedly, adiponectin expression decreases with an increase in adiposity, but levels of leptin and resistin expression increase in obesity." (PMID 35806278, 2022). "Leptin usually regulates the energy balance of the body, but in obesity, leptin is involved in pro-inflammatory processes." (PMID 34751020, 2022). "Hyperleptinemia in obesity is probably a result of the downregulation of leptin receptors, leading to leptin resistance." (PMID 36428528, 2022). "But most patients with T2DM and obesity present hyperleptinemia because the leptin levels are proportional to the body mass." (PMID 36046814, 2022). "Research showed that a CAF diet induced obesity more effectively and resulted in a more pronounced increase in the plasma leptin, TG, and cholesterol levels than the HFD protocol." (PMID 35197931, 2022). "Even though leptin levels can be considered as a systemic marker for obesity and metabolic syndrome in both genders, it is considered a more reliable diagnostic marker for different types of cancers in females." (PMID 35628271, 2022). "This paradoxical relationship between leptin and obesity can be explained by development of leptin resistance in obese individuals which become anergic to leptin signaling, resulting in loss of appetite suppression and subsequent weight gain." (PMID 36479348, 2022). "Leptin, the most studied adipokine marker of obesity, participates in the regulation of atherogenesis, thrombogenesis, and vascular revascularization." (PMID 35207618, 2022).
Obesity (continued). "Higher leptin in obesity also correlates with a decreased levels of Treg cells, resulting in more pro-inflammatory than anti-inflammatory cytokine expression, and an increased activation of neutrophils." (PMID 35795152, 2022). "Initially, most research on leptin focused on its role in regulating energy homeostasis and obesity at the central nervous system level." (PMID 35655598, 2022). "The subject with +328A variant in heterozygous condition is reported to have family history of obesity and high serum leptin level." (PMID 36619235, 2022). "Leptin and resistin play important roles in obesity and type II diabetes (T2D), and together with gastrointestinal ghrelin they regulate energy balance and body weight." (PMID 36135388, 2022). "Appetite and related hormones, such as leptin, play an active role in food intake regulation and in the occurrence of obesity in children." (PMID 36499740, 2022). "Its absence leads to a lean phenotype with resistance to diet-induced obesity, increased adipocytic lipolysis and an increased release of the protective adipokine leptin in mice." (PMID 35684088, 2022). "Leptin binds to obesity (Ob) receptors, leading to activation of JAK/STAT, PI3K, and MAP kinase signaling." (PMID 36230617, 2022). "Adipose tissue can secrete a hormone called leptin, and overweight and obesity can result in leptin resistance." (PMID 35620321, 2022). "Leptin can then induce tumor progression and metastasis through these signaling pathways in obesity-related tumors." (PMID 36230617, 2022). "Leptin is a hormone that is exclusively secreted by adipocytes, and its expression positively correlates with obesity." (PMID 35208189, 2022). "Our results suggest that the anti-resorptive action of leptin in the peripheral skeleton is the dominant effect of this adipokine at the skeleton in obesity." (PMID 36173650, 2022). "The relationship between the signaling and actions of leptin and insulin is more evident in obesity, where skeletal muscle shows resistance to leptin actions, contributing to the accumulation of lipids including intramuscular long-chain fatty acyl-CoA." (PMID 35884769, 2022). "The aim of this study is to highlight a possible correlation between obesity-specific tumor microenvironment markers (adipokine or leptin) and the different histological subtypes and aggressive characteristics of breast tumors." (PMID 35989732, 2022). "A recent study found that a fatty meal induces postprandial changes in adiponectin and leptin secretions in normal-weight subjects but not in individuals with obesity, implying that postprandial regulating role of adiponectin and leptin is reduced in obesity." (PMID 36258233, 2022). "Common murine obesity models are based on a genetically engineered deficit in Leptin signaling (ob/ob and db/db mouse) or are the result of a high caloric diet (high fat or western diet)." (PMID 36231132, 2022). "We applied a series of MR-based mediation analyses to study the role of hormonal factors—leptin and insulin resistance—in mediating the relationships between obesity and female reproductive health." (PMID 35104295, 2022). "Several metabolic and hormonal consequences of obesity, including excess levels of adipokines such as leptin and IL-6, insulin resistance, inflammation, and elevated IGF-I levels, are implicated in CRD." (PMID 36291899, 2022). "In obesity, when leptin levels are high, the number of receptors for leptin is gradually reduced and their sensitivity to this hormone decreases." (PMID 35806019, 2022). "Obesity is already known to induce low-level inflammation and increased TNFa and leptin which, if chronic, results in insulin resistance." (PMID 36584051, 2022). "The mechanisms linking peripherally derived bioactive compounds to neuronal leptin responsiveness and obesity are being intensively investigated." (PMID 35597815, 2022).
Obesity (continued). "It was found that pSTAT3 instead was more abundant in B cells from obese individuals compared to B cells isolated from lean; in B cells from lean subjects leptin induced pSTAT3 levels comparable to those observed in obesity." (PMID 35960996, 2022). "In our supplemental analysis, we found significant interactions in women between obesity status and sex hormone levels (p < 0.05 for leptin, resistin, and adiponectin)." (PMID 36712262, 2022). "Participants (n = 18) with type 2 diabetes (T2D) and class 3 obesity underwent baseline indirect calorimetry for determination of 24‐h energy expenditure, body composition, fasting serum leptin and adiponectin levels, and appetitive assessments." (PMID 36266774, 2022). "Numerous studies have been conducted on the association between polymorphism of LEPTIN, LEPR, LEPROT, and human obesity." (PMID 36011333, 2022). "The obesity is highly related to adipocytokine signals, or adipokines, such as adiponectin, visfatin, chemerin, and leptin." (PMID 35760406, 2022). "Leptin is one of the main adipokines produced by adipose tissue, and its high level participates in low-grade inflammatory processes during obesity." (PMID 35743826, 2022). "Nonetheless, other organs like the heart and kidney are known to maintain its responsiveness to leptin throughout obesity." (PMID 36855701, 2022). "A previous study showed that Igfbp6 was expressed at lower levels in obesity and was positively correlated with leptin, glucagon-like peptide 1 and cholecystokinin." (PMID 36209126, 2022). "Leptin’s influence on children’s body weight, growth rate or obesity later in life is not fully understood." (PMID 35684517, 2022). "It has been showed that obesity induces T cell dysfunction and an upregulation of PD-1 on T lymphocytes, in a partially leptin-dependent manner." (PMID 35164764, 2022). "Concentrations of leptin in cord blood of infants born to mothers with obesity was elevated compared to that of lean mothers." (PMID 36189369, 2022). "Among the clinical and biochemical parameters that we collected, we found a negative statistical correlation between MPV and BMI, MPV and leptin, which are markers of obesity and insulin resistance." (PMID 36080270, 2022). "First, obesity-mediated inflammatory cytokines, such as leptin, and activation pathways that stimulate invasion and metastasis have been suggested." (PMID 35406618, 2022). "Of note, the anorexigenic effect of LEAP-2 observed in mice exposed to HFD is in contrast to the leptin resistance usually observed in diet induced obesity." (PMID 35159134, 2022). "Leptin levels increase normally with eating; however, levels increase beyond a normal range in obesity." (PMID 35631228, 2022). "The increase of SOCS3 expression leads to the down-regulation of JAK2 pathway and the impairment of STAT3 signal, leading to leptin resistance, obesity and abnormal glucose metabolism." (PMID 36615730, 2022). "In obesity, the adipose tissue becomes an influential endocrine organ producing different factors called adipokines, such as leptin, adiponectin and kisspeptin and many others." (PMID 35743826, 2022). "The circulating concentrations of inflammation related to obesity (leptin and adiponectin) and (IL-6 and IL-10)-related biomarkers were also analyzed in this study." (PMID 35207221, 2022). "To this end, we analyze the behavior of two neuroendocrine hormones, leptin and cortisol, in a cohort of women with obesity, with simplified minimal state-space modeling." (PMID 35480480, 2022). "The obesity gene in white fat stimulates the synthesis and release of leptin, and high levels of leptin stimulate the secretion of kisspeptin." (PMID 36213197, 2022). "Animals with diet-induced obesity have reduced STAT3 phosphorylation in the ARC in response to exogenous leptin administration or inflammatory stimuli and increased basal pSTAT3 in the ARC and VMH." (PMID 35628338, 2022).